ICAM1 (intercellular adhesion molecule 1)
Diseases named in the same sentence as ICAM1 in open-access papers (continued):
Sharing a sentence is not in itself a finding about the gene and the disease.
periodontitis (37 papers, 2010 to 2026). An acute or chronic inflammatory process that affects the tissues that surround and support the teeth. "Additional investigations are needed to investigate how the ICAM-1 gene interacts with epigenetic factors in the development of periodontitis and its potential association with systemic diseases among periodontitis patients." (PMID 38650775, 2024). "AGEs, a major factor in DM complications, is thought to influence DM-associated periodontitis by regulating oxidative stress and IL-6, and ICAM-1 expression levels in HGFs." (PMID 31619000, 2019). "Porphyromonas gingivalis (P. gingivalis), one of the main pathogenic bacteria involved in periodontitis, induces the expression of intercellular adhesion molecule − 1 (ICAM-1) and monocyte-endothelial cell adhesion." (PMID 29482504, 2018). "By identifying ICAM-1 polymorphisms, it may be feasible to intervene in the context of periodontitis, potentially curbing its progression and enabling targeted treatments at the genetic level." (PMID 38650775, 2024). "Nonetheless, our recent findings for overweight or obese individuals showed a direct association between an elevated baseline serum sICAM-1 or sVCAM-1 and an indirect association between elevated baseline hs-CRP (via ICAM-1) and an increased risk of periodontitis at the 3-year follow-up visit." (PMID 37893143, 2023). "Moreover, we found a significant indirect association between elevated baseline hs-CRP (via ICAM-1) and periodontitis development/progression at the follow-up visit." (PMID 37371602, 2023). "Therefore, ICAM-1 expresion and P. gingivalis invasion in periodontal sites may be associated with the primary stages of the development and progression of chronic periodontitis." (PMID 25179218, 2014). "Studies have shown elevated ICAM-1 levels in the gingival crevicular fluid of patients with periodontitis, with expression levels correlating with inflammation severity and tissue damage." (PMID 41561951, 2025). "This study elucidates a novel pathogenic mechanism of V. parvula OMVs and highlights the potential of targeting ICAM-1+ neutrophils as a therapeutic approach for chronic periodontitis." (PMID 40568695, 2025). "There is great potential to explore the pathogenic factors of OMVs and discover other therapeutic directions for ICAM-1+ neutrophils in the treatment of chronic periodontitis." (PMID 40568695, 2025). "ICAM1+ fibroblasts expand in both human periodontitis and murine ligature-induced periodontitis model, which have upregulated expression of CCL2 and CXCL1 compared to other fibroblast populations." (PMID 39650645, 2024). "Despite the variable magnitudes in cytokine expression between species, these results demonstrate that ICAM1+ fibroblasts exhibit immune-regulatory phenotype when compared to other fibroblast populations in both humans and murine models of periodontitis." (PMID 39650645, 2024). "When ICAM1+ fibroblasts were specifically examined, we found a significant 2.4-fold increase in the periodontitis group compared to the control group, consistent with the patterns observed from the scRNA-seq dataset." (PMID 39650645, 2024). "When the scRNA-seq dataset was further stratified by individual patients, ICAM1+ fibroblast percentage was the highest at approximately at 40% in those diagnosed with periodontitis when compared to those with healthy marginal gingiva or palatal gingiva." (PMID 39650645, 2024). "Here, we identified ICAM1 as a surface marker that selectively labels fibroblasts with inflammatory signatures in both human periodontitis and experimental mouse LIP models." (PMID 39650645, 2024). "To validate ICAM1 as an in vivo surface marker for an inflammatory fibroblast subset that expands in periodontitis, we performed flow cytometry on cells prepared from freshly discarded tissues in patients with or without a periodontitis diagnosis." (PMID 39650645, 2024).
periodontitis (continued). "CCL2 was upregulated in both human and murine ICAM1+ fibroblasts, which was effectively reduced by lineage-specific deletion of Ikbkb thereby disrupting macrophage trafficking in the experimental periodontitis model." (PMID 39650645, 2024). "We next used flow cytometry to test if ICAM1 expression in fibroblasts also distinguishes an expanding inflammatory fibroblast subset in murine models of ligature-induced periodontitis (LIP)." (PMID 39650645, 2024). "Increased VCAM-1 and ICAM-1 expression recruits inflammatory cells to promote an inflammatory response and is involved in the progression of chronic inflammation and periodontitis." (PMID 37367059, 2023). "Our findings suggest direct significant associations between elevated baseline serum ICAM-1/VCAM-1 and an increased risk of periodontitis at the follow-up visit." (PMID 37371602, 2023). "Our findings suggest a positive direction for the association between the direct/indirect effect of hs-CRP, ICAM-1, and VCAM-1 and periodontitis development/progression." (PMID 37371602, 2023). "ICAM-1 and VCAM-1 gene polymorphisms have been observed in the Chinese adult population with periodontitis." (PMID 37371602, 2023). "The microvasculature subadjacent to oral epithelium expresses ICAM-1 in apparently healthy gingiva, and its expression increases during periodontitis." (PMID 32341760, 2020). "A previous study revealed that ICAM-1 rs5498 and VCAM-1 rs1041163 polymorphisms lead to chronic periodontitis." (PMID 33817202, 2019). "Our current results indicate that ICAM-1 is produced and functions during the relatively early period of periodontitis." (PMID 29091721, 2017). "Based on these results, we conclude that transfection of the NF-κB decoy ODN can suppress the overexpression of the downstream factors IL-1β, TNF-α, and ICAM-1 in the palatal gingival tissues of rats with periodontitis." (PMID 29091721, 2017). "A previous study demonstrated that ICAM1 was highly expressed in infected gingival cells as well as in tissues from periodontitis patients compared with those from healthy controls." (PMID 25483140, 2015). "In the periodontal tissues of patients with chronic periodontitis, the expression level of ICAM-1 may change due to the influence of smoking, thereby affecting the infiltration of inflammatory cells and the intensity of the inflammatory response." (PMID 41561951, 2025). "Previous research suggests that ICAM-1 might play a crucial role in the development and advancement of chronic periodontitis." (PMID 38650775, 2024). "Nevertheless, ICAM1+ fibroblasts clearly represent a specific mesenchymal subset that modulates immune responses in periodontitis, which may be useful for distinguishing inflammatory gingival fibroblasts in future studies." (PMID 39650645, 2024). "The current research indicates that there is no connection between the ICAM-1 (rs5498) gene polymorphism and periodontitis within the group under examination." (PMID 38650775, 2024). "Here, we combine the survey of published scRNA-seq data, validation assays using human gingival tissues, and a murine experimental periodontitis model to identify ICAM1 (Intercellular Adhesion Molecule 1) to be a cell surface marker that distinguishes inflammatory fibroblasts." (PMID 39650645, 2024). "The plaques from the mice with periodontitis also showed enhanced staining for adhesion molecules such as intercellular adhesion molecule-1 (ICAM-1) and vascular cell adhesion protein-1 (VCAM-1), suggesting the presence of cells with possible endothelial phenotypes in the plaques." (PMID 31257363, 2019). "ICAM-1 is an adhesive protein on the surface of the gingival and junctional epithelial cells that is an important component of adhesion between cells and the extracellular matrix, as well as cell signaling, inflammation, and immune responses in the development of periodontitis." (PMID 34832662, 2021).
periodontitis (continued). "As indicated, one could classify mutations that give rise to periodontitis due to a malfunctioning infiltration or transmigration of immune cells such as PMNs into the periodontium challenged by bacteria in the sulcus (LFA-1, ICAM-1, P-Selectin)." (PMID 29163477, 2017). "In addition, certain identified biomarkers, including IL8, IL1β, ICAM1 and VEGFA, were hub genes, therefore suggesting that they may be useful diagnostic markers for periodontitis." (PMID 25483140, 2015). "This study was conducted to explore a probable link between the genetic variations in intercellular adhesion molecule-1 (ICAM-1) represented by rs5498 and the occurrence of periodontitis." (PMID 38650775, 2024). "This study evaluated changes in inflammatory markers within GCF, including TNF-α, IL-1β, IL-6, IL-8, hs-CRP, ICAM-1, HMGB1, and PGE2, before and after treatment in patients with osteoporosis and periodontitis." (PMID 39686428, 2024). "The accumulation of AGEs in human gingival fibroblasts (HGFs) can increase the protein and mRNA expressions of intercellular adhesion molecule-1 (ICAM-1), RAGE, and ROS through the NF-κB signaling pathways and MAPK pathways and aggravate periodontitis." (PMID 37664859, 2023). "Previous research indicated that the expression of ICAM1 is regulated by certain inflammatory cytokines, including IL-1β and TNF-α, and that ICAM-1 plays an important role in the initial stage of periodontitis." (PMID 29091721, 2017). "We also showed overexpression of IL1B, TNFα, ICAM1, and RANKL mRNA in the palatal gingival tissues of periodontitis model rats, which is consistent with previous reports." (PMID 29091721, 2017). "We further examined the spatial distribution of ICAM1+ fibroblasts by immunofluorescence and found increased numbers of ICAM1+ fibroblasts to be localized around inflammatory foci in periodontitis but not in healthy groups." (PMID 39650645, 2024). "In advanced human periodontitis, T and B/plasma cells predominate, for which CXCL13 and CCL19 expression from the ICAM1+ fibroblasts may be important as they are chemotactic for B and T cells, respectively." (PMID 39650645, 2024). "Considering this, the objective of the present study is to assess whether the interaction of baseline serum levels of TNF-α, hs-CRP, ICAM-1, VCAM-1, and adiponectin leads to periodontitis among overweight/obese individuals." (PMID 37371602, 2023). "Thus, elevated serum ICAM-1 and VCAM-1 have a significant direct effect and increased hs-CRP has a significant indirect effect on the predicted level of periodontitis at the 3-year follow-up among overweight/obese Hispanic adults." (PMID 37371602, 2023). "The objective of this study is to assess whether the interaction of baseline serum levels of TNF-α, hs-CRP, ICAM-1, VCAM-1, and adiponectin leads to periodontitis." (PMID 37371602, 2023). "Recent studies showed that VCAM-1 and ICAM-1 are expressed in the connective tissue cells, like gingival fibroblasts and human PDL cells, which may be related to the progression of periodontitis." (PMID 34185172, 2022). "In addition, ICAM‐1 and VCAM‐1 are involved in leukocyte‐endothelial cell adhesion, and increased levels of these molecules have been observed in the GCF of individuals with periodontitis compared with periodontally healthy individuals." (PMID 40344491, 2025). "As the focus of our study was on characterizing the identity and role of these fibroblasts in experimental periodontitis, we did not explore the downstream events of ICAM1 activation via cell-to-cell contact mechanism with other immunocytes which is well characterized." (PMID 39650645, 2024). "For example, it can be suggested to study the role of epithelial ICAM-1 on healthy periodontium, the impact of the SCFA receptors in this context, and whether butyrate produced by periodontal pathogens plays a role in pathogenesis of periodontitis." (PMID 32121422, 2020).
periodontitis (continued). "Several cytokines, including tumour-necrosis factor-α (TNF-α), IL1, IL6, IL8, intercellular adhesion molecule-1 (ICAM-1), monocyte chemoattractant protein-1 (MCP-1), and granulocyte-macrophage colony-stimulating factor (GM-CSF), play important roles in the development process of periodontitis." (PMID 26705104, 2015). "The observation that the periodontal bone loss in aging WT mice correlates with significant changes in the expression of Del-1, but not of ICAM-1, VCAM1, or E-selectin, further supports the notion that the age-associated Del-1 deficiency is an important determinant of age-associated periodontitis." (PMID 24416060, 2013).
depression (36 papers, 2015 to 2025). "Brain NO increased significantly (p < 0.05) in depression and anxiety and was associated with an ICAM-1 increase versus naive (p < 0.05) and a Sirt1 decrease (p < 0.05) versus naive." (PMID 38396638, 2024). "Higher levels of ICAM-1 and VCAM-1 have also been associated with schizophrenia, depression, and bipolar disorder, and interestingly, higher ICAM-1 levels have been associated with BBB hyper-permeability." (PMID 36904292, 2023). "A recently published meta-analysis including 9,203 people with depression, found an association between higher ICAM-1 levels and depression." (PMID 36387880, 2022). "Our current study extends this finding to show that TBI-induced ICAM-1 activation is associated with impairment in sensorimotor function and depression and anxiety-like psychological stress disturbances." (PMID 34135004, 2021). "Negative psychological factors were related to higher average methylation in ICAM-1 promoter regions (with the associations for anxiety significant at the 0.10 level and for depression significant at the 0.05 level)." (PMID 26733571, 2016). "On the other hand, ICAM-1 is a pro-inflammatory molecule, which might be a useful biomarker for depression associated with vascular inflammation." (PMID 37836393, 2023). "ICAM-1 has also been found to be a predictor of depression risk following traumatic brain injury." (PMID 37921965, 2023). "Psychological distress measured by anxiety, depression and hostility was positively associated, and happiness and life satisfaction were inversely associated with average Intercellular Adhesion Molecule-1 (ICAM-1) and coagulation factor III (F3) promoter methylation levels." (PMID 26733571, 2016). "ICAM-1 was the only marker which early-stage AD control had significantly more than depression control, showing that ICAM-1 level in the DLPFC is increased with age, which is also consistently with the previous finding in the orbitofrontal cortex." (PMID 40179065, 2025). "The majority of previous studies reported either unchanged or elevated expression of VCAM-1 and ICAM-1, or their soluble forms, in major depression and bipolar disorder." (PMID 39056795, 2024). "While little evidence exists about the implications of membrane-bound ICAM-1 in the CNS, the blood levels of sICAM-1 were found to be increased in patients with depression." (PMID 38396638, 2024). "Second, the co-morbid presentation of depression with PD is extensively documented, and the involvement of ICAM-1 in late-life depression has been verified." (PMID 39329738, 2024). "Patients with major depressive disorder typically exhibit higher levels of adhesion molecules related to proinflammatory conditions like ICAM-1, while those with bipolar disorder show an increase in anti-inflammatory molecules like VCAM-1." (PMID 39056795, 2024). "The increase in NO expression in the brain NO increase was associated with an increase in ICAM-1 and a decrease in SIRT1, but only in the depression state." (PMID 38396638, 2024). "We measured three tight cell junction proteins (JAM-A, claudin 5 and occludin), and additionally the ICAM-1/collagen IV ratio in the later-life depression and later-life control groups." (PMID 37700368, 2023). "Levels of ICAM-1 were shown to be increased in the orbitofrontal cortex of patients with depression." (PMID 36549907, 2023). "Soluble ICAM-1 is increased in the blood of patients with depression, bipolar disorder, and dementia." (PMID 37628746, 2023). "Previous studies have also reported elevated levels of ICAM-1 in CSF or serum in psychiatric disorders such as schizophrenia and major depressive disorder." (PMID 36895367, 2023). "The upregulation of adhesion molecules, including ICAM-1, and the possible role of vascular pathology in depression development have been studied." (PMID 37921965, 2023). "According to the results of our study, ICAM-1 cannot be considered one of the elements linking depressive disorder and COPD." (PMID 37921965, 2023).